SDC1 (syndecan 1)
Diseases named in the same sentence as SDC1 in open-access papers (continued):
Sharing a sentence is not in itself a finding about the gene and the disease.
hepatocellular carcinoma (continued). "In addition, serum levels of syndecan-1 are raised in hepatocellular carcinoma (HCC) patients compared with cirrhotic patients." (PMID 38022112, 2023). "The suppression of SDC1 induces the downregulation of the CSC markers CD133, CD44, and CD90, while the hepatoma spheres size is drastically decreased." (PMID 36358747, 2022). "In hepatocellular carcinoma, SDC1 and SDC4 are key for migration, invasion and increased motility mediated by chemokine-SDC interactions." (PMID 33494442, 2021). "In hepatocellular carcinoma (HCC) cells, high HPSE expression was shown to induce necroptosis in adjacent microvascular endothelial cells (MVECs), thereby promoting trans-endothelial migration through the HPSE/SDC-1/TNF-α and p38 MAPK pathways." (PMID 41301515, 2025). "In this manuscript we focused on the changes of syndecan-1 developed in hepatocellular carcinoma with and without cirrhosis, as well as on its change as the response of tumor metastasis." (PMID 30826971, 2020). "Compared to normal liver areas increased amount of syndecan-1 could be observed both in cirrhosis and non-cirrhosis based hepatocellular carcinoma, however it is much higher in the former, where syndecan-1 expression is also high in the peritumoral cirrhotic areas." (PMID 30826971, 2020). "In patients with advanced hepatocellular carcinoma (HCC), serum levels of SDC1 were increased compared to those without HCC or with early HCC." (PMID 26293675, 2015). "Therefore, we transduced a gene of PR-39 into human hepatocellular carcinoma cell line HLF, which shows a low expression of syndecan-1 and a high in vitro invasive activity, and examined whether this procedure could reduce the invasive activity of tumour cells." (PMID 10507762, 1999).
chronic endometritis (40 papers, 2014 to 2026). A non-granulomatous or granulomatous chronic inflammation of the endometrium. "Description of CD-138 structure: CD-138, syndecan-1, is a protein evaluated in endometrial biopsies for detecting subclinical chronic endometritis." (PMID 38529432, 2024). "The immunohistochemical presence of plasma cells (CD138, also known as syndecan-1) in endometrial specimens is thought to be an objective diagnosis of chronic endometritis." (PMID 37174948, 2023). "Our primary objectives were to evaluate the relevance of hysteroscopy and conventional histology compared to immunohistochemical expression of syndecan-1 (CD138, a marker of plasma cells), which is a heparan sulfate proteoglycan involved in inflammation and enables diagnosis of chronic endometritis." (PMID 41032339, 2025). "They showed that immunohistochemistry for the transmembrane heparan sulfate proteoglycan syndecan-1 (CD138) improved the diagnostic accuracy of chronic endometritis compared with morphological analysis without immunohistochemistry." (PMID 24558386, 2014). "Out of the nine selected studies, four exclusively employ immunohistochemistry (IHC) for diagnosing chronic endometritis, utilizing the CD138 marker (syndecan-1)." (PMID 39286255, 2024).
melanoma (40 papers, 2012 to 2025). A malignant, usually aggressive tumor composed of atypical, neoplastic melanocytes. "Histological analysis at melanoma metastases further suggested that CD31+/aminopeptidase N+/syndecan-1+/integrin β4+ phenotypes were associated with vascular structures." (PMID 32756007, 2020). "Previously, we had shown the decreased expression of syndecan-1 (SDC1) was mediated by PKCδ that promoted loss of cell invasiveness for melanoma A375 cells under anchorage-independency." (PMID 28977882, 2017). "We hypothesized that the regulation of ANPEP, SDC1, and integrin β4 expression might associate with loss of vasculogenic phenotype upon suspension of melanoma cells." (PMID 32756007, 2020). "In a comparative study of Syndecan-1 and angiogenesis-associated B-fibronectin isoform expression in melanoma tissues, using OC-46F2 and L19 antibodies, respectively, we observed that some vessels were positive with the anti-Syndecan-1 antibody but negative with L19." (PMID 26460958, 2015). "In a xenograft melanoma model, it has been demonstrated that the combination of L19-IL-2 with anti-SDC1 OC-46F2 mAb resulted in the complete inhibition of melanoma growth for up to three months after tumor injection in 71% of the treated mice." (PMID 39852848, 2025). "For example, in malignant melanoma, treatment with an antibody–drug conjugate that targets Sdc1, showed anti-tumor effects by inhibiting vascular maturation." (PMID 36009225, 2022). "Sdc1 is overexpressed during early chronicity and therefore indicates increased tumor-like mobility in keratinocytes, reminiscent of melanomas." (PMID 36009225, 2022). "Sdc1 in chronic wounds autoactivates ErbB2, which is a characteristic of melanoma, suggesting that as wounds become chronic, they show many characteristics of cancer." (PMID 36009225, 2022). "For example, application of the Sdc-1-targeting monoclonal antibody OC-46F2 curtails vascular maturation and tumor growth in mouse models of human melanoma and ovarian cancer." (PMID 34066023, 2021). "The combinative polypeptide CBD–HepII inhibits expression of αVβ3 and SDC-1, thus decreasing interactions between these two receptors in B16 melanoma cells and inhibiting pulmonary metastasis of tumor cells in the circulation." (PMID 35118073, 2021). "Previously, we showed that LLC cells have high expression of SDC1 and CASP11, with strong susceptibility to SCGB3A2-induced anti-tumor activity, whereas B16F10 melanoma cells have very little expression of SDC1 and CASP11, and no susceptibility to SCGB3A217." (PMID 33452234, 2021). "Our previous studies showed suspended melanoma cells had reduced SDC1 expression but exhibited higher potential at xenograft tumor growth through elevated IL-8 levels." (PMID 32756007, 2020). "Nevertheless, these indicated the expression axis ANPEP/SDC1/integrin β4 existed in melanoma cells, which was downregulated by anchorage independence." (PMID 32756007, 2020). "The human antibody OC-46F2, specific for the ectodomain domain of SDC1, has proved to inhibit tumor growth in experimental human models of melanoma and ovarian carcinoma by blocking angiogenesis." (PMID 32916872, 2020). "Previously, we demonstrated that anchorage-independence of melanoma cells impaired their laminin-binding ability through downregulation of SDC1." (PMID 32756007, 2020). "Our previous study suggested melanoma cell suspension contributed to reduced laminin-binding ability through downregulation of SDC1 protein." (PMID 32756007, 2020). "In summary, we suggested the expression axis of aminopeptidase N/syndecan-1/integrin β4 in melanoma cells was suppressed by detachment stress, which diminished vascular phenotypes of melanoma metastases." (PMID 32756007, 2020). "Previously, we had shown that the downregulation of SDC1 protein was mediated by the PKCδ activation in suspended melanoma cells." (PMID 32756007, 2020).
melanoma (continued). "We previously reported the therapeutic efficacy of anti-syndecan-1 scFv OC-46F2 on experimental human melanoma and ovarian carcinoma models in NOD SCID mice." (PMID 31443604, 2019). "In a human melanoma and ovarian cancer experimental model, the human antibody OC-46F2, specific for the extracellular domain of SDC1, blocked vessel maturation and tumor development." (PMID 31412643, 2019). "Downregulation of syndecan-1 and upregulation of syndecan-2 in melanoma A375 cells were observed by different suspension conditions." (PMID 28977882, 2017). "We show that melanoma cells lose their ability to form tubule-like structures in vitro after blocking syndecan-1 activity by the specific human recombinant antibody, OC-46F2." (PMID 26460958, 2015). "To specifically recognize all human melanoma cells, we used anti-human NuMA antibody and we observed a strong expression of Syndecan-1 and VEGFR-2 in NuMA positive melanoma cells." (PMID 26460958, 2015). "We recently demonstrated that Syndecan-1 is a potential therapeutic target in melanoma and ovarian carcinoma." (PMID 26460958, 2015). "We observed an increased Syndecan-1 mRNA expression in human melanoma cells isolated from murine lung metastases (MeTA met) compared to the injected cells (MeTA)." (PMID 26460958, 2015). "In fact, preclinical experiments of therapy in subcutaneous graft models of melanoma and ovarian carcinoma showed that scFv OC-46F2, specific for the ectodomain of Syndecan-1, inhibited vascular maturation and tumor growth." (PMID 26460958, 2015). "We demonstrated that Syndecan-1 positive melanoma cell lines having a vasculogenic and a stem cell-like phenotype, express two molecules involved in melanoma VM, such as CD144 and VEGFR-2." (PMID 26460958, 2015). "In this study we observed, in melanoma patient cell lines having vasculogenic/stem-cell like phenotype and in melanoma tumors, the syndecan-1 co-expression with VM markers, such as CD144 and VEGFR-2." (PMID 26460958, 2015). "As a pharmacological approach an inhibitory antibody against syndecan-1 has been developed and successfully used to block melanoma growth and ovarian carcinoma." (PMID 26378057, 2015). "In fact, we observed a positive staining in primary oesophageal and metastasis melanoma with the plasma cell markers CD138/syndecan-1, MUM1, and immunoglobulin lambda light chain." (PMID 23133774, 2012). "Similar VEGF activation by SDC1 occurs in melanoma and ovarian carcinoma." (PMID 32916872, 2020). "Since SDC1 level also affected the laminin-binding ability and it was downregulated in suspended melanoma, we checked whether SDC1 expression level would affect laminin-binding integrin expression." (PMID 32756007, 2020). "Previously, we reported that targeting SDC1 using the human recombinant antibody scFv (single chain Fragment variable) OC-46F2 was able to inhibit tumor growth in melanoma and human ovarian carcinoma models induced in NOD SCID (Non-Obese Diabetic Severe Combined Immunodeficiency) mice." (PMID 31443604, 2019). "Recently we established a possible role of SDC1 in VM of melanoma and that combined therapy could improve the therapeutic efficacy of both anti-SDC1 scFv OC-46F2 antibody and immunocytokine L19-IL2, specific for B-FN, administered as single agents." (PMID 31443604, 2019). "We recently reported that blocking Syndecan-1 activity via the human specific antibody scFv OC-46F2 leads to an antitumor effect by inhibiting vascular maturation and tumor growth in experimental human melanoma and ovarian carcinoma models." (PMID 26460958, 2015). "Syndecan-1 expression correlates to increased metastatic potential in melanoma cells." (PMID 26460958, 2015). "Furthermore, the in vitro and in vivo experiments have shown that the antibody OC-46F2 was able to inhibit human melanoma VM and to block the pro-angiogenic activity of Syndecan-1." (PMID 26460958, 2015).
melanoma (continued). "We recently reported that the human recombinant antibody, scFv OC-46F2, specific for the ectodomain of Syndecan-1, exerts an antitumor activity in vivo by reducing tumor growth and vascular maturation in experimental human melanoma and ovarian carcinoma murine models." (PMID 26460958, 2015). "The expression of CD138/syndecan-1 in melanoma is reported in only one case." (PMID 23133774, 2012). "Although it was demonstrated that ANPEP, SDC1, and integrin β4 were associated with vessel formation/angiogenesis, our results suggested the sequential expression of ANPEP/SDC1/integrin β4 through PKCδ activation determined the vasculogenic phenotype of melanoma cells." (PMID 32756007, 2020). "Moreover, we observed that in human melanoma xenograft, targeting SDC1 via scFv OC-46F2 enhanced the therapeutic efficacy of L19-IL2, an immunocytokine composed of an scFv specific for the angiogenesis-associated B-fibronectin isoform and IL2, inhibiting tumor growth and VM processes." (PMID 31443604, 2019). "Moreover, in a human melanoma xenograft model, we observed that the anti-syndecan-1 antibody OC-46F2, administered either as monotherapy or in combination with the immunocytokine L19-IL2, inhibited tumor growth, inducing a dramatic decrease of vascular density and loss of VM structures." (PMID 31443604, 2019). "The completely humanized SDC-1 recombinant antibody OC-46F2 reduces SDC-1/VEGFR-2 activity in tumor microenvironments, consequently blocking vascular maturation and tumor growth in the setting of malignant melanoma and experimental models of ovarian cancer." (PMID 35118073, 2021). "In this study, we found that anchorage-independence of melanoma cells downregulated aminopeptidase N (ANPEP) expression, which downregulated SDC1 expression, thus further downregulated integrin β4 expression." (PMID 32756007, 2020). "We tested melanoma cell lines SKMEL28, MV3 and melanoma cells isolated from ten patients, all positive for Syndecan-1, to form tubule-like structures on Matrigel." (PMID 26460958, 2015). "We found that the combination therapy using the OC-46F2 anti Syndecan-1 blocking antibody and the immunocytokine L19-IL2 leads to a complete inhibition of tumor melanoma growth until day 90 from tumor implantation in 71% of treated mice." (PMID 26460958, 2015). "Syndecan-1, is a modified heparan sulfate proteoglycan (HSPG) that DV uses to infect cells that is upregulated on tumor cells and increases the migratory potential of melanoma cells." (PMID 37468934, 2023). "The expression of SDC1 and SDC2 in different melanoma cells were examined." (PMID 28977882, 2017). "In a study on human skin cancers, Syndecan-1 (SDC1) expression was reduced in squamous cell carcinoma, basal cell carcinoma, as well as metastatic adenocarcinomas, and the downregulated expression of this protein may be indicative of reduced lipid metabolism in melanoma." (PMID 41155412, 2025).
colorectal cancer (38 papers, 2008 to 2025). A primary or metastatic malignant neoplasm that affects the colon or rectum. "Further studies reported that SDC1 shedding is enhanced as a response to chemotherapy and shed SDC1 was found to be associated with chemotherapy resistance in colorectal cancer." (PMID 33114033, 2020). "In a number of reports decreased epithelial Sdc1 expression was associated with an advanced clinical stage of colon tumors or poor prognosis, while one study associated epithelial Sdc1 immunopositivity with increased tumor size in colorectal carcinoma." (PMID 28350804, 2017). "Results from a recent meta-analysis of colorectal cancer studies demonstrated that loss of syndecan-1 expression in colorectal cancer correlates with histological grade and tumor stage, but not with lymph node or distant metastasis." (PMID 26869927, 2016). "In colorectal carcinoma, low epithelial expression of syndecan-1 is associated with a higher histological grade, with more advanced clinical stage of the patients, and with potentially more unfavorable prognosis." (PMID 26869927, 2016). "Syndecan-1 shedding is increased in colorectal cancer and the loss of epithelial syndecan-1 is associated with advanced clinical stage and poor prognosis." (PMID 26420915, 2015). "In agreement with other analyses of colorectal carcinoma, loss of epithelial syndecan-1 correlated with tumor TNM stage and incidence of metastases to local lymph nodes." (PMID 18590537, 2008). "Our findings from a large, clinically annotated tissue microarray of colorectal carcinoma specimens add to the body of evidence that loss of epithelial syndecan-1 is a general feature of carcinoma progression." (PMID 18590537, 2008). "Hovewer, low cell surface syndecan-1 level is associated with a poor prognosis as demonstrated by immunohistochemistry in lung cancer, renal carcinomas, head and neck cancer, and in colorectal cancer." (PMID 24392351, 2013). "Previous literature has reported varied expression of SDC1 in different cancers, with decreased expression in gastric and colorectal cancers but increased expression in plasmacytoid urothelial carcinoma and pancreatic cancer." (PMID 39238647, 2024). "In gastric and colorectal cancers, the overexpression of SDC1 has been found to inhibit cancer cell growth." (PMID 38162504, 2023). "SDC1 is low expressed in gastric cancer and colorectal cancer, whereas SDC1 is highly expressed in plasmacytoid urothelial carcinoma, liver cancer, and glioma." (PMID 35432485, 2022). "The objective of this study was to evaluate the relation between syndecan-1 immunoexpression and several clinicopathological parameters in a subset of colorectal carcinoma (CRC) patients." (PMID 33437261, 2021). "In colorectal cancer cells, high expression of Sdc-1 reduced tumor growth and invasion through down-regulation of MAPK and Stat3 signaling." (PMID 33330449, 2020). "Syndecan-1 expression is dysregulated in a number of cancers, including head and neck, ovarian, breast, and colorectal carcinomas." (PMID 26869927, 2016). "On the other hand, in colorectal cancer shed syndecan-1 induces resistance to chemotherapy via the EGFR pathway." (PMID 26420915, 2015). "Syndecan-1 plays a vital role in the suppression, transformation, and migration of several cancer types, including colorectal cancer (CRC)." (PMID 26518017, 2015). "We also examined the relationship between syndecan-1 and a recently identified novel independent prognostic factor for colorectal carcinoma, fascin." (PMID 18590537, 2008). "Similarly, in human colorectal cancer, serum SDC1 levels serve as a prognostic biomarker for stages II and III, but not for stage IV." (PMID 41364407, 2025). "Syndecan-1 (SDC1) is a cell surface multifunctional proteoglycan that was found to exert a protective function against the development of colorectal cancer in a murine model of inflammation and carcinogenesis (chemically induced by administering azoxymethane + dextran sodium sulfate, AOM/DSS)." (PMID 35454809, 2022).